CHEK1 (checkpoint kinase 1)
Diseases named in the same sentence as CHEK1 in open-access papers (continued):
Sharing a sentence is not in itself a finding about the gene and the disease.
pancreatic cancer (74 papers, 2009 to 2026). "This analysis is complemented by molecular biology experiments, including cellular clone formation assays, to thoroughly investigate the role of CHEK1 in pancreatic cancer and its underlying mechanisms." (PMID 41564103, 2026). "Taken together, the analyses suggest that the CHEK1 gene is linked to survival in pancreatic cancer patients and can serve as a reliable independent prognostic factor." (PMID 41564103, 2026). "As the patient had pancreatic cancer (died at 33 y) and his sister had osteogenic sarcoma at an early age (13 y, unavailable for genotyping), the CHEK1 p.Q346Ter is a likely candidate variant for cancer predisposition in this family." (PMID 38654924, 2024). "Curcumin, a component of turmeric, derived from the rhizomes of Curcuma longa inhibits proliferation of human pancreatic cancer cells by activation of Ataxia telangiectasia mutated (ATM)/checkpoint kinase 1 (ChK1)/Cdc25C, blocking cyclin B1/Cdk1 activity and arresting cells at G2/M check point." (PMID 28946660, 2017). "Subsequently, we validated the impact of CHEK1 on the malignant biological behaviors of pancreatic cancer cells, specifically focusing on proliferation and migration, through a series of in vitro cellular experiments." (PMID 41564103, 2026). "The findings offer novel insights into the function of CHEK1 in pancreatic cancer and its influence on patient clinical outcomes." (PMID 41564103, 2026). "In summary, integrated bioinformatics evidence from multiple databases collectively indicates that CHEK1 plays a crucial role in pancreatic cancer progression and patient prognosis." (PMID 41564103, 2026). "While CHEK1 abnormalities have been extensively documented across various tumor types, their precise biological role in pancreatic cancer remains inadequately understood." (PMID 41564103, 2026). "Together these data demonstrated that CHEK1 plays an important role in promoting pancreatic cancer growth." (PMID 41564103, 2026). "We conducted a systematic investigation into the expression characteristics and biological functions of CHEK1 in pancreatic cancer, utilizing an integration of bioinformatics analyses and in vitro experiments." (PMID 41564103, 2026). "In summary, high CHEK1 expression in pancreatic cancer correlates with higher pathological grades and predicts poor outcomes." (PMID 41564103, 2026). "This study aims to elucidate CHEK1’s role in pancreatic cancer using tools like multi-network and regression analyses, functional experiments, and flow cytometry analysis." (PMID 41564103, 2026). "Functional experiments demonstrated that CHEK1 overexpression enhances pancreatic cancer cell growth, whereas its knockdown inhibits it, confirming its critical regulatory role." (PMID 41564103, 2026). "Despite numerous studies on CHEK1 in various cancers, its expression and prognostic role in pancreatic cancer remain underexplored." (PMID 41564103, 2026). "The findings revealed that CHEK1 expression levels were significantly upregulated in pancreatic cancer tissues, which correlated positively with tumor pathological grade." (PMID 41564103, 2026). "Initially, we performed an in-depth analysis of CHEK1 expression profiles and their clinical significance in pancreatic cancer, drawing on data from several public databases, including UALCAN, TNMplot, and TISIDB." (PMID 41564103, 2026). "In summary, CHEK1 exhibits elevated expression levels in pancreatic cancer and is positively correlated with the pathological grade of patients diagnosed with this malignancy." (PMID 41564103, 2026). "Subsequently, we used flow cytometry to assess the effect of CHEK1 on the cell cycle of pancreatic cancer." (PMID 41564103, 2026). "To identify appropriate cell lines for subsequent functional experiments, we initially assessed the expression levels of CHEK1 across various pancreatic cancer cell lines utilizing the CCLE dataset." (PMID 41564103, 2026).
pancreatic cancer (continued). "This study found that CHEK1 expression was significantly higher in pancreatic cancer tissues than in normal tissues andcorrelated positively with tumor grade." (PMID 41564103, 2026). "CHEK1, a crucial cell cycle regulator, is important in tumor development, but its role in pancreatic cancer remains under-researched in terms of expression, function, and regulation." (PMID 41564103, 2026). "In vitro experimental demonstrated that CHEK1 overexpression substantially increased both the proliferative progression and migratory capacity of pancreatic cancer cells." (PMID 41564103, 2026). "The results showed that that CHEK1 expression in pancreatic cancer was significantly correlated with tumor proliferation, G2M checkpoint, DNA replication and DNA repair." (PMID 41564103, 2026). "Further research is needed to explore CHEK1-related molecular pathways to support targeted clinical interventions for pancreatic cancer." (PMID 41564103, 2026). "To elucidate the biological function of CHEK1 in pancreatic cancer cells, we established CHEK1-knockdown and overexpression models toassessed cellular phenotypes, focusing on proliferation and the cell cycle." (PMID 41564103, 2026). "We evaluated the expression of TMC7 and CHEK1 AS events in pancreatic cancer cell lines and normal pancreatic cell lines by qRT-PCR." (PMID 36713450, 2022). "Pancreatic cancer (Mia-PaCa2) cells exposed to 5 μM gemcitabine for 24 hours showed increased phosphorylation of CHEK1 at serine 317 and 345, which is indicative of CHEK1 activation." (PMID 30112106, 2018). "Consistent with previous studies, we also identified checkpoint kinase 1 (CHK1) inhibitors as GEM-sensitizing PKIs in pancreatic cancer MIA PaCa-2 cells." (PMID 23855452, 2013). "Recently, a high throughput RNAi screen identified the checkpoint kinase 1 (CHK1) as a gene conferring resistance to gemcitabine in pancreatic cancer cells." (PMID 22244109, 2012). "Thus, CHEK1 is an independent prognostic factor for pancreatic cancer, distinct from traditional clinicopathological parameters." (PMID 41564103, 2026). "Clinical characteristics of CHEK1 in Pancreatic cancer samples." (PMID 41564103, 2026). "Our study indicates that high CHEK1 expression could be an independent prognostic marker for pancreatic cancer and may drive cancer progression by influencing DNA replication and G2/M checkpoint pathways." (PMID 41564103, 2026). "Furthermore, G2/M checkpoint abrogation using checkpoint kinase 1 (CHK1) inhibitors is known to increase the RT efficacy in preclinical models of pancreatic cancer, colorectal cancer, bladder cancer, and TNBC." (PMID 32294924, 2020). "Similarly, a study using CHEK1 inhibitor AZD7762 showed that gemcitabine administration either concurrent with or before AZD7762 resulted in maximal chemosensitization in pancreatic cancer model." (PMID 25884494, 2015). "The preceding analysis indicates that CHEK1 could potentially serve as an independent prognostic factor in pancreatic cancer.Therefore, we constructed a nomogram incorporating CHEK1, which was identified as significant in the multifactorial Cox regression analysis, to facilitate clinical prognosis." (PMID 41564103, 2026). "We conducted an in-depth analysis of the impact of CHEK1 on the migratory behavior of PANC-1 and MIA PaCa-2 pancreatic cancer cell lines using the transwell migration assay." (PMID 41564103, 2026). "For example, it has been shown that gemcitabine resistance can be induced by the activation of checkpoint kinase 1 (CHK1) and regulation of the cell cycle via the MMP/ERK1/2 signaling pathway in pancreatic cancer cells grown in a 3D collagen matrix." (PMID 39334952, 2024). "The inhibitions of some DDR molecules, such as CHK1 (checkpoint kinase 1) and ATR, have been demonstrated to enhance the effect of GEM in resistant pancreatic cancers." (PMID 33182492, 2020).
pancreatic cancer (continued). "The aim of this study was to determine whether checkpoint kinase 1 inihibitor (CHK1), LY2603618, and gemcitabine prolong overall survival (OS) compared to gemcitabine alone in patients with unresectable pancreatic cancer." (PMID 28202004, 2017).
lung carcinoma (71 papers, 2010 to 2026). "The genomic alteration/mutation analysis of 11 hub-DEGs revealed that the EGFR, MYC, and CHEK1 genes had 12%, 8%, and 1.3% genomic alteration/mutation over the four lung cancer studies." (PMID 35632527, 2022). "The CHEK1 mutations primarily occurred in lung cancer, spanning the Pkinase domain, with the hotspots in T226Nfs*19, T226Hfs*14, and E223G." (PMID 32178478, 2020). "Up-regulation of CHEK1 by reduced expression of miR-195 promotes cell proliferation, migration, and invasion, and is associated with a higher overall mortality in lung cancer." (PMID 28486418, 2017). "High levels of CHEK1 expression in lung cancers were linked to a shorter survival time." (PMID 37986065, 2023). "Notably, CHEK1 inhibition is synthetically lethal with loss of B-Family DNA Polymerases like POLE2 in lung cancer and colorectal cancer cells." (PMID 34853396, 2021). "Previous studies in lung cancer have demonstrated that CHEK1 activates the Snail transcription factor, which suppresses E-cadherin and upregulates N-cadherin and Vimentin, thereby inducing EMT and promoting tumor cell migration and invasion." (PMID 41564103, 2026). "Researchers found that miR-195 directly targets Checkpoint kinase 1 (CHEK1), reducing CHEK1 expression in lung cancers." (PMID 37986065, 2023). "According to previous literatures, ISLR promotes colorectal cancer (CRC) progression; SNAIL1 promotes GC cell proliferation and migration; and CHEK1 is up-regulated in lung cancer and inhibits the radiotherapy sensitivity of GC cells." (PMID 35739527, 2022). "The CDC6, CDC20, and CHEK1 genes are closely related to the occurrence and development of small-cell lung cancer, and CHEK1 is treated as a therapeutic target for lung cancer." (PMID 35632527, 2022). "CHEK1 has been shown to be highly expressed in lung cancer cells, and importantly, miR-195 has been demonstrated to inhibit the progression and development of NSCLC by targeting CHEK1." (PMID 31528122, 2019). "We also identified a target of miR-195, CHEK1, and demonstrated that miR-195 down-regulated its expression and delayed cell cycle progression in lung cancer cells." (PMID 25840419, 2015). "First, to our best knowledge, this is the first report showing that miR-195 suppressed NSCLC through, at least partially, down-regulating the expression of CHEK1, a newly discovered target in lung cancer." (PMID 25840419, 2015). "We discovered that CHEK1 was a direct target of miR-195, which decreased CHEK1 expression in lung cancer cells." (PMID 25840419, 2015). "On the other hand, the genomic alteration/mutation analysis of the hub-DEGs reflected that most mutation for the EGFR occurred across the four lung cancer studies and was followed by the MYC and CHEK1 genes, since EGFR is a highly mutant/altered gene for lung cancer and NSCLC as well." (PMID 35632527, 2022). "Overexpression of CHEK1 in lung cancers was related to poor overall survival." (PMID 29321960, 2018). "CHEK1 is a direct target of miR-195, which results in decreased CHEK1 expression in lung cancer." (PMID 28486418, 2017). "CHEK1 inhibitors have been tested as therapeutic agents for several types of cancer including lung cancer, and the test results show that the inhibitors may affect the sensitivity of radiotherapy and chemotherapy." (PMID 25840419, 2015). "In lung cancer patients with cisplatin resistance, the upregulation of USP51 diminishes γH2AX formation and increases checkpoint kinase 1 (CHK1) phosphorylation, thereby ensuring an effective cell cycle." (PMID 38702734, 2024). "GEPIA online software was used to analyze the expression of CHEK1, CCNB1, CCNB2, and CDK1 in 969 lung cancer tissues (including lung adenocarcinoma and lung squamous cell carcinoma) and 685 normal lung tissues." (PMID 36714024, 2023). "Kaplan–Meier plotter was used to analyze the prognosis of the core genes CHEK1, CCNB1, CCNB2, and CDK1 in patients with lung cancer." (PMID 36714024, 2023).
lung carcinoma (continued). "CHEK1, CCNB1, CCNB2, and CDK1 are the critical core genes of lung cancer and are highly expressed in lung cancer." (PMID 36714024, 2023). "Combined with the results of this study, it can be inferred that CHEK1, CCNB1, CCNB2, and CDK1 are critical genes involved in cell cycle arrest and DNA damage repair in lung cancer." (PMID 36714024, 2023). "The expression of CHEK1, CCNB1, CCNB2, and CDC2 was negatively correlated with the prognosis of patients with lung cancer (P < 0.01)." (PMID 36714024, 2023). "The microarray datasets GSE7670, GSE151102, GSE33532, GSE43458, and GSE19804 were further analyzed to determine the accuracy and reliability of the related expression of the four essential core genes (CHEK1, CCNB1, CCNB2, and CDK1) in lung cancer." (PMID 36714024, 2023). "In line with our data derived from primary tumor specimens, we found that SCLC cell lines display significantly higher levels of CHEK1 expression, than NSCLC and non-lung cancer cell lines." (PMID 29138515, 2017). "Additionally, CHEK1 has been shown to regulate TUBB protein levels, in which CHEK1 overexpression was shown to increase TUBB protein levels in lung cancer cell lines." (PMID 36140469, 2022). "In addition, the correlation between KLC4 and CHEK1, CHEK2 was investigated in both lung cancer and cervical cancer using RNA-sequencing data from publicly available microarray datasets." (PMID 32457423, 2020). "Therefore, CHEK1, CCNB1, CCNB2, and CDK1 may be helpful prognostic biomarkers for lung cancer." (PMID 36714024, 2023).
colorectal cancer (66 papers, 2007 to 2026). A primary or metastatic malignant neoplasm that affects the colon or rectum. "Notably, reduced CHEK1 mRNA expression is significantly associated with poor clinical prognosis in patients with gastric and colorectal carcinomas, underscoring its potential utility as a prognostic indicator and therapeutic target." (PMID 41235705, 2025). "In the present study, the combination of ataxia telangiectasia-mutated serine/threonine kinase (ATM) and checkpoint kinase 1 (Chk1) inhibition exhibited synergistic antitumor effects and induced synergistic lethality in colorectal cancer cells at a low dose." (PMID 36765693, 2023). "CHEK1 has some anti-apoptotic ability, and a positive correlation between CHEK1 overexpression and tumor malignancy and poorer prognosis has been noted in colorectal cancer." (PMID 36874006, 2023). "TRAF4 was found to catalyze the ubiquitination of the DNA-damage checkpoint kinase 1 (CHK1) at the K132 site to induce its phosphorylation and activation, resulting in chemotherapy resistance in colorectal cancer." (PMID 36535926, 2022). "The prognosis analysis result showed that reduced CHEK1 mRNA expression is an unfavorable prognostic factor for patients with gastric and colorectal cancer." (PMID 32178478, 2020). "The study demonstrated that the CHEK1 gene was differentially expressed in four different cancers, and that reduced CHEK1 mRNA expression is an unfavorable prognostic factor for patients with gastric and colorectal cancer." (PMID 32178478, 2020). "Additionally, the co-expression profiles for CHEK1 with 20 genes across 36 colorectal carcinomas, 45 colorectal adenocarcinomas, and 24 normal colorectum tissues were investigated." (PMID 32178478, 2020). "Several lines of evidence suggest that CHEK1 responded to DNA damage by initiating cell cycle arrest, thus providing time for cells to repair damage and escape cell withering before restoring cell cycle, which has prognostic significance in human colorectal cancer." (PMID 35991881, 2022). "Upon DNA damage, CHK1, the CHEK1 lncRNA-associated mRNA, enables cell cycle arrest and DNA damage repair; thus, its inhibition may confer therapeutic targeting of CSCs in many cancer types, including PDAC, colorectal cancer, prostate cancer, non-small-cell lung cancer, and acute myeloid leukemia." (PMID 36831395, 2023). "In colorectal cancer, TRAF4 catalyzes the ubiquitination of Checkpoint Kinase 1 (CHK1), which is required for CHK1 phosphorylation and ATR activation following DNA damage." (PMID 36077559, 2022). "Interestingly, CHEK1 was co-expressed with minichromosome maintenance complex component (MCM family) and flap eendonuclease 1 (FEN1) expressed in colorectal cancer." (PMID 32178478, 2020).
colon carcinoma (57 papers, 2007 to 2025). "Studies revealed that cancer-associated defects of CHEK1 are extremely rare, and so far seem limited to carcinomas of the colon, stomach, and endometrium." (PMID 32178478, 2020). "Two of the three cell lines most sensitive to RAD17 knockdown were GP2D and LS411N, both colon cancer cell lines harboring CHEK1 mutation." (PMID 26437225, 2015). "Camptothecin is an analogue of the standard-of-care chemotherapeutic irinotecan used to treat colon cancer, and CHEK1 inhibitors can potentiate responses of DNA-damaging compounds through abrogation of DNA damage-induced cell cycle arrest." (PMID 35197630, 2022). "This damage can be strong enough to induce checkpoint kinase 1 activation and G2/M arrest in colon cancer cells through the activation of the ataxia-telangiectasia mutated (ATM) protein kinase when DNA damage is not repaired." (PMID 34456713, 2021). "Depletion of checkpoint kinase-1 (Chk1) by siRNAs, transfection with dominant-negative Chk1 mutants or pharmacological Chk1 inhibition killed tetraploid colon cancer cells yet had minor effects on their diploid counterparts." (PMID 18159231, 2007). "However, downregulation of miR-195 in colon cancer cell lines can suppress the viability of cancer 5-FU-resistant cells by increasing CHEK1 and might be considered as a treatment in colon cancer." (PMID 35087589, 2022). "We engrafted three colon cancer cell lines (LS-1034, SW837 and SNU-81) in NOD/SCID mice and treated them for 24–35 days with irinotecan (TOP1 inhibitor), rabusertib (CHEK1 inhibitor), or with a combination of the two drugs." (PMID 35197630, 2022).